ATRX (ATRX chromatin remodeler)
Diseases named in the same sentence as ATRX in open-access papers (continued):
Sharing a sentence is not in itself a finding about the gene and the disease.
oligodendroglioma (93 papers, 2012 to 2026). A well-differentiated (WHO grade II), diffusely infiltrating neuroglial tumor, typically located in the cerebral hemispheres. "These genetic alterations distinguish oligodendrogliomas from diffuse astrocytomas, which lack the 1p/19q co-deletion and often harbor ATRX mutations." (PMID 40937216, 2025). "Additional molecular markers, such as 1p/19q co-deletion and ATRX mutations, can aid in the diagnosis of oligodendrogliomas." (PMID 40949165, 2025). "One of the ATRX-deficient samples with MMR-d (case #17) was a recurrent tumor showing oligodendroglioma-like morphology and harboring fusions involving the NTRK2 and LRRFIP2 genes." (PMID 37891325, 2023). "Both the primary and recurrent tumors showed oligodendroglioma-like morphology as well as ATRX loss." (PMID 37891325, 2023). "Consistent with a previous report, the high predicted probability score (0.9835) indicated that the loss of H3K27me3 with ATRX positivity is frequent to IDH1-R132H Mut 1p/19q codeleted oligodendroglioma." (PMID 34020723, 2021). "On the other hand, five oligodendroglioma tumors (with functional ATRX and a mutation in hTERT), measured with a C-circle score of 0 AU, did not exhibit ALT-specific ultra-bright Telo-FISH foci." (PMID 31706351, 2019). "Co-deletion of 1p/19q was recently shown to be associated with CIC and FUBP1 mutations, mainly seen in oligodendroglioma and mutually exclusive with ATRX mutation." (PMID 24810474, 2014). "Furthermore, ATRX mutations are specific to astrocytoma and help differentiate them from oligodendrogliomas, where 1p19q codeletion rarely co-occurs with ATRX mutations." (PMID 40013192, 2025). "Notably, ATRX (X-linked nuclear protein) mutations are rare in oligodendrogliomas and are mutually exclusive with TERT since both these two genes target the lengthening telomeres." (PMID 35875065, 2022). "For oligodendroglioma, out of 10 cases, IDH mutation was positive, and ATRX was retained in all cases." (PMID 39165459, 2024). "By contrast, ATRX-WT/ 1p-19q co-deleted oligodendrogliomas exhibited weaker correlations with these immune-related transcriptional signatures." (PMID 38272925, 2024). "A DNA methylome profile of oligodendroglioma, IDH-mutant and 1p/19q-codeleted, a retained nuclear expression of ATRX and a TERT promoter mutation are desirable criteria." (PMID 36717507, 2023). "In IDH-mutant tumours, ATRX+ was 100% sensitive and 87% specific to oligodendrogliomas, while ATRX+/H3K27me3− was 96% sensitive and 100% specific." (PMID 34165590, 2021).
oligodendroglioma (continued). "83.3% (15/18) of oligodendrogliomas and 69.8% (30/43) of oligoastrocytomas showed ATRX positivity even in a background of intact 1p/19q." (PMID 27556304, 2016). "Defines oligodendroglioma lineage (ATRX intact, TERT-mut); these tumors are chemo-sensitive." (PMID 41346390, 2025). "ATRX expression was retained in all cases of oligodendrogliomas." (PMID 39165459, 2024). "The tumors presented IDH1 (R132H) mutations detected by IHC and Sanger sequencing (performed for the primary tumor only) and showed nuclear immunopositivity of ATRX in consistence with the 2021 WHO classification criteria for the diagnosis of oligodendroglioma, IDH-mutant and 1p/19q-codeleted." (PMID 36739454, 2023). "In our study, TERTp mutations were found in 100% of O_IDH_mut and 6.3% of A_IDH_mut cases, while ATRX mutations were present in 82.1% of A_IDH_mut cases but not in oligodendrogliomas." (PMID 37185778, 2023). "Given the low incidence of ATRX mutations in oligodendrogliomas, none of these cases were predicted to have loss of ATRX on IHC or Foundation Medicine." (PMID 36397144, 2022). "Immunohistochemical analysis for H3K27me3, ATRX, and IDH1-R132H revealed that diffuse gliomas with a loss of nuclear H3K27me3 staining, retained ATRX staining, and IDH1-R132H positivity can be predicted as 1p/19q codeleted oligodendrogliomas with a probability score of 0.9835." (PMID 34020723, 2021). "Finally, IDH‐WT GBs, oligodendroglial tumours and pilocytic astrocytomas all retained ATRX protein expression in the nucleus." (PMID 31111685, 2020). "IHC for ATRX was available for 13 of the oligodendroglioma cases and all showed preservation of ATRX while only 3 cases (including the one for which IHC was not available) had Foundation Medicine results, none of which showed mutations in ATRX." (PMID 36397144, 2022).
oligodendroglioma (continued). "IDH1 R132H immunohistochemical and ATRX stains are now available at AKUH and at least two other laboratories in the country and will hopefully facilitate the diagnosis of oligodendroglioma." (PMID 38764578, 2024). "For oligodendroglioma, out of 10 cases, IDH was positive and ATRX was retained in 100% of the cases." (PMID 39165459, 2024). "Thirty-five out of 39 oligodendroglioma cases that were positive for IDH1-R132H and ATRX, and reduced H3K27me3, exhibited 1p/19q codeletion." (PMID 34020723, 2021). "Our prediction models indicate the clinical utility of H3K27me3 IHC for the prediction of IDH1-R132H Mut 1p/19q codeleted oligodendroglioma along with IDH1-R132H and ATRX IHC." (PMID 34020723, 2021). "When a diffuse glioma has whole‐arm 1p/19q co‐deletion (ie, molecular evidence of oligodendroglioma), is it still necessary to assess the IDH and ATRX status as well?" (PMID 24990071, 2014). "For oligodendroglioma, IDH was positive, and ATRX was retained in all cases." (PMID 39165459, 2024). "Conversely, the ATRX-intact and TERTp-mutant oligodendroglioma PDCs were negative for C-circle amplification." (PMID 32904945, 2020). "In diffuse ATRX+ oligodendrogliomas, no more than 5–10% of tumour cells showed variably positive nuclear, perinuclear and cytoplasmic staining." (PMID 31111685, 2020). "Subsequently, we investigated the overall performance of our MLPA cutoff criteria in association with the features typical for oligodendrogliomas (oligodendroglial histology, IDH and TERT mutations and no ATRX loss)." (PMID 29923492, 2018).
neuroblastoma (83 papers, 2008 to 2026). Neuroblastoma (NB) is the most common solid, extracranial childhood tumor. "In conclusion, these results consistently indicate that ATRX mutations associate with higher expression of genes related to an inflammatory immune response and infiltration of cells of myeloid lineage in neuroblastoma patient datasets." (PMID 39892705, 2025). "Alongside an inflammatory phenotype, we also show that in neuroblastoma models both ATRX LoF and ATRX IFF’s are associated with upregulation of genes associated with epithelial-to-mesenchymal transition." (PMID 39892705, 2025). "Next, we used xCell tool (gene signature-based method) to investigate the tumor immune microenvironment of ATRX-mutated neuroblastomas in the same patient cohort." (PMID 39892705, 2025). "ATRX loss-of-function in MYCN amplified neuroblastoma was shown to be synthetically lethal in mouse models and cell lines." (PMID 40286729, 2025). "Since myeloid cells are increasingly recognized as key effectors for both antibody and CAR-T mechanisms of action in solid cancers, future studies will need to characterize the effector phenotype of the infiltrating myeloid cells in ATRX-mutated neuroblastoma." (PMID 39892705, 2025). "The commonest type of ATRX alterations in neuroblastoma are in-frame multi-exon deletions, followed by nonsense mutations predicted to result in loss-of-function (ATRX LoF)." (PMID 41380652, 2025). "ATRX and TERT mutations are more commonly found in patients older than the age of 18 months, with TERT being associated with stage 4 disease and ATRX being associated with a refractory clinical subtype – all of which are unfavourable signs of neuroblastoma." (PMID 40653949, 2025). "To unravel the role of ATRX in neuroblastoma, we generated isogenic neuroblastoma cell line models with ATRX loss-of-function and ATRX in-frame multi-exon deletions, representing different types of alterations found in patients." (PMID 39892705, 2025). "The mechanisms underlying how ATRX mutations drive high-risk and difficult-to-treat neuroblastoma are still largely elusive." (PMID 39892705, 2025). "ATRX alterations are identified in 10 % of high-risk neuroblastomas and associated with poor outcomes." (PMID 41380652, 2025). "In all neuroblastoma cases, ATRX alterations are closely associated with alternative lengthening of telomeres (ALT), chronic metastatic disease and poor outcome." (PMID 39892705, 2025). "In a previous study, ATRX mutations were associated with loss of the nuclear ATRX protein in neuroblastoma." (PMID 40286729, 2025). "ALT is also active in about 24% of high-risk neuroblastomas, about half of which are associated with somatic alterations in ATRX." (PMID 40115016, 2025). "In recent years it has become apparent that in neuroblastoma ATRX mutations define a distinct patient subgroup that are mutually exclusive with MYCN amplification, associated with older age at diagnosis and a chronic progressive disease course." (PMID 39892705, 2025). "Recent studies have shown that in neuroblastoma 68 % of ATRX mutations are multi-exon deletions, most commonly resulting in loss of exons 2–10 of the gene, and resulting in an in-frame fusion (IFF) protein with gain of function oncogenic effects." (PMID 39892705, 2025). "ATRX mutations are identified in a range of malignant tumors, such as neuroblastoma, pancreatic neuroendocrine tumors, and osteosarcoma." (PMID 39479502, 2024). "Our findings implicate 11q loss and strong 17q gain in ALT neuroblastomas and show that these alterations deregulate ATRX interaction partners." (PMID 39635126, 2024).
neuroblastoma (continued). "Among participants achieving CR, all received combination therapy (mTOR inhibitor with chemotherapy in rhabdomyosarcoma with PI3K or FGFR4 gain-of-function mutations; irinotecan combination therapy in neuroblastoma with an ATRX mutation)." (PMID 38755180, 2024). "This attenuation of gene expression allows ATRX-mutated neuroblastoma cells to proliferate continuously." (PMID 39479502, 2024). "The neuroblastoma samples were previously evaluated for ATRX and DAXX mutations, and MYCN amplification." (PMID 38837897, 2024). "ATRX mutations have been observed in neuroblastomas, pancreatic neuroendocrine tumors and pediatric osteosarcomas." (PMID 37812190, 2023). "ATRX is a commonly mutated gene in pediatric cancer and its precise molecular role in neuroblastoma development is still unclear." (PMID 37540673, 2023). "In contrast to other pediatric cancer where ATRX point mutations are most frequent, multi-exon deletions (MEDs) are the most frequent type of ATRX aberrations in neuroblastoma." (PMID 37540673, 2023). "ATRX aberrations are strongly associated with ALT and all neuroblastomas with ATRX aberrations tested so far utilize this telomere maintenance mechanism." (PMID 37540673, 2023). "ATRX in frame deletion mutations that result in deletion of the PHD finger have been reported in neuroblastoma and osteosarcoma cancers." (PMID 35998910, 2022). "It would be worth analyzing the sensitivity to these drugs in other cancer types presenting ATRX mutations, such as hepatocellular carcinoma, pancreatic neuroendocrine tumors, and neuroblastomas, and in cells with different genetic backgrounds." (PMID 35406561, 2022). "In the high-risk neuroblastoma genome, there are few additional recurrent mutations other than ATRX (7.1% deletion, 2.5% mutation), or PTPN11 (2.9%)." (PMID 36185250, 2022). "To detect alterations associated with telomere maintenance, a crucial mechanism of neuroblastoma tumor biology, we selected probes to detect ATRX mutations or deletions, as well as TERT rearrangements." (PMID 34442335, 2021). "For example, in neuroblastomas, ATRX loss-of-function mutations play a role in ALT which is related to worse prognosis." (PMID 35087762, 2021). "Some well-known chromatin remodeling proteins include ARID1A/B and ATRX, which is one of the few known mutational targets in neuroblastoma." (PMID 34885007, 2021). "Loss of function mutations, or the deletion of ATRX has also been shown to sensitise neuroblastoma cell lines and PDXs to the current standard-of-care drug irinotecan, in combination with the PARP inhibitor olaparib." (PMID 34064704, 2021). "Third, ATRX mutations in neuroblastomas are often in-frame deletions that remove approximately half of the amino terminus of the protein." (PMID 32060267, 2020). "In neuroblastoma, genetic alterations in ATRX are associated with a distinct clinical phenotype including older age at diagnosis and a chronic progressive disease course." (PMID 32375866, 2020). "Regarding common mutations in neuroblastoma, both tumors at time of stabilization and progression harbored ATRX mutation." (PMID 32354143, 2020). "The hydra approach also identified an association between ATRX deletions and elevated immune marker expression in high-risk neuroblastoma." (PMID 32275708, 2020). "There is a strong association between ALT and loss of function (LoF) genetic alterations in ATRX (Alpha Thalassemia mental Retardation-X linked) in multiple malignancies, including neuroblastoma." (PMID 32375866, 2020). "We propose that MYCN amplification and ATRX mutations are incompatible in neuroblastoma, because both lead to DNA-replicative stress." (PMID 32060267, 2020).